ZNF446 (zinc finger protein 446)
Description:
May be involved in transcriptional regulation.
Synonyms: ZKSCAN20; FLJ20626; ZSCAN52
Tractability: PROTAC: UniProt records ubiquitination sites on it; ubiquitination databases record sites on it.
Gene: Protein-coding gene on chromosome 19 (58,474,017 to 58,481,233, forward strand). Ensembl gene ENSG00000083838.
Subcellular location: Nucleus
Subcellular location (Human Protein Atlas): Nuclear speckles
Pathways (Reactome):
Gene expression (Transcription): Generic Transcription Pathway
Gene Ontology:
Molecular function: protein binding; DNA-binding transcription factor activity, RNA polymerase II-specific; RNA polymerase II cis-regulatory region sequence-specific DNA binding
Biological process: regulation of transcription by RNA polymerase II; regulation of DNA-templated transcription
Cellular component: extracellular region; nuclear speck; chromatin; nucleus
Genetic constraint (gnomAD): Loss-of-function variants: 45 observed, 39.02 expected, observed/expected ratio (o/e) 1.15, 90% interval 0.91 to 1.48. The synonymous counts are far from expectation, so gnomAD's model fits this gene poorly and the ratio says little. Missense variants: 650 observed, 595.74 expected, observed/expected ratio (o/e) 1.09, 90% interval 1.02 to 1.16. Synonymous variants: 315 observed, 253.15 expected, observed/expected ratio (o/e) 1.24, 90% interval 1.13 to 1.37.
Homologues: Orthologues: chimpanzee ZNF446 (98% identical), macaque ZNF446 (94% identical), rabbit ZNF446 (63% identical), pig ZNF446 (60% identical), rat Zfp446 (58% identical), guinea pig ZNF446 (57% identical), mouse Zfp446 (55% identical), Drosophila melanogaster CG12391 (15% identical), Drosophila melanogaster hb (13% identical), zebrafish ovol1a (11% identical), zebrafish ovol1b (10% identical), zebrafish plagl2 (9% identical), and 4 more. Paralogues in human: ZNF202 (35% identical), ZNF18 (30% identical), ZKSCAN2 (28% identical), ZSCAN18 (28% identical), ZSCAN32 (27% identical), ZNF496 (26% identical), ZSCAN29 (26% identical), ZNF274 (25% identical), ZSCAN1 (24% identical), ZNF174 (23% identical), ZNF444 (23% identical), ZSCAN5C (21% identical), and 17 more.
Diseases named in the same sentence as ZNF446 in open-access papers:
ZNF446 is named in the same sentence as 5 diseases in open-access papers, as found by Europe PMC text mining. Sharing a sentence is not in itself a finding about the gene and the disease. The quoted sentences say what the papers report.
Uric acid nephrolithiasis (1 paper, 2017). The presence of uric acid-containing calculi (stones) in the kidneys. "Moreover, strong association of UACl with ZNF446 itself is interesting because studies have shown association of ZNF365, on chromosome 10, with urolithiasis in children, and with uric acid nephrolithiasis in adults." (PMID 28095793, 2017).
tumor (2 papers, 2020 to 2022). "In general, a significant decrease in the ZNF473 and ZBTB32 transcriptionlevels is observed in tumor as compared to healthy tissue (theMann–Whitney p-value is < 0.02 in both cases and >0.4 in ZNF446).These genes can act as markers for germ cell-derived tumors." (PMID 36348719, 2022). "In addition, we identify the KRAB zinc finger protein, ZNF446, and its associated tripartite motif protein, TRIM27, as obligate components of the ZNF165-SMAD3 complex that also support tumor cell viability." (PMID 32515734, 2020). "In addition, an endogenous interaction between ZNF165 and ZNF446 was detectable in TNBC tumor cell nuclear extracts, confirming these proteins interact in the relevant subcellular compartment." (PMID 32515734, 2020). "No clear patterns of changesin the ZNF446 transcription were found during tumor formation." (PMID 36348719, 2022).
ZNF446 also shares sentences with these, for which no sentence is quoted: breast carcinoma (1 paper); breast tumors (1); urolithiasis (1).